HNF1A (HNF1 homeobox A)
Diseases named in the same sentence as HNF1A in open-access papers (continued):
Sharing a sentence is not in itself a finding about the gene and the disease.
diabetes (continued). "Based on Condel functionality scores and centrality positions in genetic interaction networks, two prominent candidates in diabetes mellitus and maturity-onset diabetes of the young (MODY)—HNF1A rs2464195 and HNF4A rs147638455—were identified." (PMID 41376825, 2025). "Among the perturbations correlated with HNF1A overexpression is ALOX5 overexpression, which also impacts beta cell function in diabetes via increased insulin resistance." (PMID 40504147, 2025). "We focused our efforts primarily on pancreatic beta cells and secondarily on hepatic cells, as these cells are central to diabetes biology and provide a biologically relevant context for the study of HNF4A and HNF1A." (PMID 38909044, 2024). "Improved insight into the mechanism of disease has been important to enable precision diabetes treatment for several of these disorders, e.g., sulphonylurea agents for the treatment in K-ATP neonatal diabetes, HNF4A-MODY, and HNF1A-MODY." (PMID 38855865, 2024). "By contrast, GIGYF1, HNF1A and HNF4A are involved with lower level cellular processes which have a less immediate impact in terms of producing diabetes as a phenotype." (PMID 39666780, 2024). "The strongest evidence for a precision approach was, in order, HNF1A-diabetes, GCK-related hyperglycemia, relapse of 6q24-TND, and SLC19A2-diabetes." (PMID 39025920, 2024). "Similar to HNF1A MODY, the rate of diabetes complications in patients with HNF4A MODY is directly related to glycemic control and is comparable to that of patients with T1D or T2D." (PMID 39408828, 2024). "There were 12 studies that contributed to data on treatment for GCK-related hyperglycemia, 23 studies for HNF1A-diabetes, and three studies for HNF4A-diabetes (with several studies contributing data to more than one diabetes subtype)." (PMID 39025920, 2024). "This monogenic diabetes panel analysis identified chr7: 44149977 G>A, GCK (NM_000162.5: c.571C>T, p.Arg191Trp) and chr12: 120999468 G>A, HNF1A (NM_000545.8: c.1624-15G>A| NM_001306179.2: c.1630G>A, p.Ala544Thr) in the patient." (PMID 39089324, 2024). "This indicates excellent discrimination between Type 1 diabetes or Type 2 diabetes and the 3 common monogenic diabetes subtypes GCK, HNF1A, HNF4A collectively, as well as when comparing Type 1 and Type 2 diabetes with HNF1A/4A and GCK etiologies separately." (PMID 37794142, 2023). "We aimed to develop a robust approach for determining the pathogenicity of variants of uncertain significance in hepatocyte nuclear factor-1 alpha (HNF1A)-MODY and to obtain an accurate estimate of the prevalence of HNF1A-MODY in paediatric cases of diabetes." (PMID 37798422, 2023). "The current understanding of HNF1A function has emerged primarily from studies of this transcription factor in the context of mature-onset diabetes of the young 3 (MODY3) and the risk for diabetes mellitus (DM)." (PMID 37219942, 2023). "The genetic content of the monogenic diabetes NGS panel used is recommended to include at least the 5 common diagnoses (GCK, HNF1A, HNF1B, HNF4A, and m.3243A>G)." (PMID 37033247, 2023). "The most common forms of monogenic diabetes, HNF1A, HNF4A, and GCK etiologies, are dominantly inherited, and the vertical transmission of diabetes or hyperglycemia is often evident in the pedigree." (PMID 37794142, 2023). "Bei Patient:innen mit HNF1A MODY war der Sulfonylharnstoff Gliclazid um den Faktor 5 wirksamer als Metformin, und um den Faktor 4 wirksamer als bei klassischem Typ 2 Diabetes." (PMID 37101022, 2023). "With this unicentric cohort study, we intended to evaluate the accuracy of MPC for the screening of monogenic diabetes subtypes GCK, HNF1A and HNF4A MODY." (PMID 35822264, 2022). "In our whole study, 16/297 (5.4%) of patients had monogenic diabetes due to either a partial or whole gene deletion (14 HNF1B, 1 HNF1A and 1 HNF4A)." (PMID 34789499, 2022).
diabetes (continued). "The analysis revealed that GCK-MODY patients have a more similar metabolomic pattern to healthy individuals than to patients with other forms of diabetes (HNF4A-MODY, HNF1A-MODY and type 2 diabetes)." (PMID 35179657, 2022). "Previous studies have shown that UCPCR can be used to determine hepatocyte nuclear factor 1alpha (HNF1α) and HNF4α for distinguishing between maturity-onset diabetes of the young (MODY) and other types of diabetes." (PMID 36465621, 2022). "Previous studies suggested that MODY probably accounts for 1–5% of overall diagnosed diabetes, with the most commonly reported subtypes as GCK-MODY (MODY2), HNF1A-MODY (MODY3), and HNF4A-MODY (MODY1)." (PMID 35921062, 2022). "In that study, CRP enabled differential diagnosis of HNF1A-MODY, with a receiver operating characteristic curve-derived C-statistic for discrimination between HNF1A-MODY and other diabetes types of 0.86 (95% confidence interval: 0.83, 0.88)." (PMID 36104811, 2022). "In both T1D and T2D, we found enrichment of monogenic forms of diabetes, as expected —2 genes in T1D (RASGRP1, INS) and 8 in T2D (HNF1B, GCK, WFS1, KCNJ11, ABCC8, HNF1A, PPARG, SLC2A2)." (PMID 33836063, 2021). "High-sensitivity C-reactive protein (hs-CRP) levels are lower in HNF1A-MODY and have been tested in some studies to discriminate HNF1A-MODY from other types of diabetes, although more data are needed." (PMID 32528556, 2020). "Elevated expression of miR-224 in HNF1A-MODY and patients with T1DM, first reported by us as a novel miRNA in the field of diabetes, presents a potential role for miR-224 in beta-cell failure, distinct from relative insulin deficiency." (PMID 31969632, 2020). "HNF1A-MODY is typified by transient neonatal hyperinsulinemic hypoglycemia, progressive development of hyperglycemia during childhood, and onset of diabetes mellitus by 25 years of age." (PMID 33292863, 2020). "This high rate of editing unlocks the potential to directly model dominant or gain of function alleles identified in humans in founder pigs produced by SSC editing, exemplified by our choice to engineer HNF1a and INS to model dominant forms of diabetes." (PMID 33584819, 2020). "HNF4α has been reported to play a key role in controlling hepatic CES2 expression in diabetes, obesity, or NASH; thus, we also investigated and found that HNF1α positively regulates CES2 expression though much need to be done in the future (data not shown)." (PMID 31223625, 2019). "More genes are shared between pairs of phenotypes: NPP1, AKT2 between diabetes and obesity, HNF1A, INSR and PPP1R3A between ovarian cysts and diabetes, and PTEN between ovarian cysts and obesity." (PMID 31307376, 2019). "Hepatocyte nuclear factor 1A (HNF1A) maturity‐onset diabetes of the young (MODY) is a monogenetic, autosomal dominantly inherited form of diabetes." (PMID 31483937, 2019). "A correct molecular diagnosis is of utmost importance, since subjects with HNF1A-MODY are usually very sensitive to oral treatment with sulphonylurea derivatives (SU) such as gliclazide, which can provide excellent diabetes control for decades." (PMID 29666556, 2018). "Protein truncating variants robustly co-segregate with diabetes, but with an increased age of onset compared to HNF1A-MODY, as only 27% had developed diabetes by age 25, compared to 55% of HNF1A-MODY cases." (PMID 30377832, 2018). "In those with HNF1A/HNF4A-MODY, a shorter diabetes duration, lower HbA1c and lower BMI at genetic diagnosis predicted successful treatment with sulfonylurea/diet alone, supporting the need for early genetic diagnosis and treatment change." (PMID 30229274, 2018). "Additionally, as expected, lower LDL-c levels were observed in HNF1A-DM patients than in patients with non-HNF1A-DM forms of diabetes, while HDL-c levels were higher than those in female T2DM patients." (PMID 30155490, 2018).
diabetes (continued). "In conclusion, in this study we calculated a minimum prevalence of 66 (95% CI 61 - 72) HNF1A-MODY cases per million of population in Croatia, which is consistent with the estimated prevalence of this form of monogenic diabetes in other European countries." (PMID 29666556, 2018). "Among 4 study participants identified to have HNF1A-MODY and treated with insulin, 2 were changed from insulin to an SU treatment and their diabetes remains well controlled." (PMID 29666556, 2018). "Similar to HNF1A/HNF4A-MODY6, 38, RFX6-MODY patients lack islet autoantibodies and have isolated diabetes." (PMID 29026101, 2017). "Between diabetes groups in OTU taxa, we observed that the frequency of Turicibacterales was significantly higher in HNF1A-MODY group than in T2DM group and in the first control group than in T2DM group." (PMID 27807544, 2016). "Having established which of the circulating miRNAs seem to be dependent on HNF1A or HNF1B defects, we set about replicating the findings in our UK group of patients with monogenic diabetes." (PMID 27059371, 2016). "Plasma ghrelin level is higher in HNF1A–MODY and GCK–MODY than in the common polygenic forms of diabetes." (PMID 25987348, 2015). "In summary we report in this study the generation of mouse db/db iPSCs as well as patient-specific HNF1A MODY reprogrammed cells which could be considered as important tools for investigation of molecular mechanisms responsible for pathophysiology of different types of diabetes." (PMID 25716801, 2015). "Fresh serum samples from a total of 37 monogenic diabetes patients (21 from GCK-MODY and 16 from HNF1A-MODY), 22 T1DM patients and 15 healthy individuals were measured in this study." (PMID 24549415, 2014). "Overall, we were able to obtain 42 fresh serum samples from patients with monogenic diabetes: 22 from GCK-MODY and 16 from HNF1A-MODY groups." (PMID 24549415, 2014). "sCD36 was also significantly lower in HNF1A-MODY participants when compared to both the normoglycaemic family controls and to lean participants with type 2 diabetes mellitus." (PMID 24069322, 2013). "In the UK replication study, we did not observe a difference in cystatin C levels between the UK HNF1A-MODY and other diabetes types, except HNF1B-MODY." (PMID 22350134, 2013). "HNF1A-MODY participants were lean, normotensive, with higher HDL and lower triglyceride levels when compared to controls and participants with type 2 diabetes mellitus." (PMID 24069322, 2013). "There is a significant clinical overlap between patients with hepatocyte nuclear factor (HNF)-1A and HNF4A maturity-onset diabetes of the young (MODY), two forms of monogenic diabetes." (PMID 23803251, 2013). "The aim of this study was to determine levels of sCD36 in participants with HNF1A-MODY diabetes and to compare them with unaffected normoglycaemic family members and participants with type 2 diabetes mellitus." (PMID 24069322, 2013). "We also demonstrated elevated serum levels of PSP/reg1A, the human homologue of PSP/reg, in human subjects with HNF1A-MODY and in subjects with type 1 diabetes mellitus, suggesting that the endocrine pancreas is the primary source of this signal." (PMID 22808921, 2012). "We analysed serum PSP/reg1A levels and correlated with clinical and biochemical parameters in subjects with HNF1A-MODY, glucokinase (GCK-MODY), and type 1 diabetes mellitus." (PMID 22808921, 2012). "This was not surprising as low renal threshold is seen clinically in this form of diabetes and attributed to reduced expression of the low affinity/high-capacity glucose co-transporter (SGLT2) which is regulated by HNF1A." (PMID 22859960, 2012). "The interdependent function of Hnf1α and Hnf4α is also relevant to our understanding of how haploinsufficiency of HNF1A and HNF4A leads to β-cell dysfunction and diabetes." (PMID 20523905, 2010). "Our study predicts a common islet transcriptome defect in the pathophysiology of HNF1A and HNF4A diabetes." (PMID 20523905, 2010).
diabetes (continued). "Given that metformin, a first-line therapy for diabetes, is transported into the liver by OCT1, it is possible that HNF1α genetic variations could influence metformin bioavailability and drug elimination." (PMID 40149950, 2025). "In the HNF1A‐MODY family in our study, the age of diabetes onset decreased progressively across generations (from an average of 39 in the second to 29 in the third generation), which may suggest genetic anticipation." (PMID 41497485, 2025). "For example, heterozygous Hnf1a knockout mice display only mild glucose intolerance and do not fully reproduce the diabetes phenotype seen in humans with HNF1A-MODY." (PMID 41199860, 2025). "In a prospective study on HNF1A-diabetes (n = 27) and HNF4A-diabetes (n = 7) not on SU at diagnosis, 25 of the 31 patients on insulin discontinued insulin but only 12 (48%) achieved an HbA1c of 7.5%23." (PMID 39025920, 2024). "There are no studies on drug-naïve newly-diagnosed patients with HNF1A- or HNF4A-diabetes comparing the different treatment options." (PMID 39025920, 2024). "The patient’s mother, although a carrier of the same molecular defect in the HNF1A gene, had neither diabetes nor POF." (PMID 38311659, 2024). "While five studies included both HNF1A-diabetes and HNF4A-diabetes, only three studies (16 individuals) had HNF4A-diabetes data that could be extracted." (PMID 39025920, 2024). "In a USA study, monogenic diabetes genetic screening approach was modeled as being cost-effective at 6% yield and cost-saving at 30% yield for GCK, HNF1A, HNF4A, with an estimated combined prevalence of 2%, implicating the most clinically actionable changes to therapy." (PMID 37794142, 2023). "A clinical prediction model (MODY probability calculator) has been developed previously, using 594 Europeans with HNF1A, HNF4A or GCK monogenic diabetes and 597 with types 1 and type 2 diabetes, and can be used to derive the pre-test probability of monogenic diabetes." (PMID 37033247, 2023). "For example, neonatal onset (directed neonatal diabetes gene panel testing); retrospective mild fasting hyperglycaemia (characteristic of GCK); high HDL (HNF1A); neonatal macrosomia (HNF4A) and syndromic features present in patients with either HNF1B or mitochondrial forms (MIDD)." (PMID 37033247, 2023). "In contrast to the age-related phenotype of HNF1A/HNF4A-MODY, GCK-MODY causes life-long stable mild fasting hyperglycemia from birth with a modest increase with age rather than true progressive diabetes as seen in HNF1A/HNF4A-MODY." (PMID 36257325, 2022). "Due to the marked family history for diabetes, a genetic investigation in the suspicion of MD was initially performed, using Sanger sequencing for HNF4A-, HNF1A-, and GCK-MODY, but no mutations were found." (PMID 36294752, 2022). "The role of HNF1A in the gut in diabetes has not been well investigated; however, ghrelin, an appetite-stimulating hormone produced primarily in the stomach and intestine, is a potential target of HNF1A." (PMID 35328643, 2022). "We calculated Cox proportional hazard ratios (HR) for developing diabetes in HNF1A/4A heterozygotes relative to individuals without HNF1A/4A pathogenic variants in each of the three clinically unselected cohorts." (PMID 36257325, 2022). "HNF1A-MODY is a type of nonketotic diabetes characterized by progressive hyperglycemia in childhood, adolescence, and early adulthood and has a high risk of chronic microvascular complications." (PMID 35299962, 2022). "Furthermore, several genes involved in the endocrine specification and diabetes development were significantly downregulated, such as HES1, INSM1, HNF1A, NEUROD1, NGN3, NKX2.2, GIPR, MNX1, PROX1, TCF7L2, and HHEX." (PMID 33473118, 2021). "These included several genes not previously implicated in diabetes, GIGYF1, TNRC6B and PFAS, as well as GCK, HNF1A and PDX1, known MODY genes." (PMID 34732801, 2021).
diabetes (continued). "With the establishment of sulfonylureas as the treatment of choice for HNF1A-MODY, molecular diagnosis of monogenic diabetes has been solidified as a necessary clinical tool with important prognostic implications, being part of clinical routine for patients with a clinical suspicion of MODY." (PMID 32528556, 2020). "This study, however, did not compare HNF1A diabetes with HNF4A, which bears many clinical similarities between each other." (PMID 32528556, 2020). "Levels of hsCRP are lower in HNF1A-MODY than in other types of diabetes (including other types of MODY) and nondiabetic subjects." (PMID 32528556, 2020). "Diagnosing HNF1A‐MODY accordingly may prevent H‐HCA‐related complications, and allow for correct diabetes treatment for both the patient and his or her family." (PMID 31483937, 2019). "Positive β-auto-antibodies (IA-2) were reported in 25% (7/28) of HNF1α patients, and these patients develop diabetes much later than those with negative autoantibody." (PMID 29867778, 2018). "There are case reports of decades of successful treatment on SU therapy in HNF1A-MODY, although clinicians also, not infrequently, see cases who do not respond well despite possessing an HNF1A variant that is clearly diabetes-causing (personal observation)." (PMID 30377832, 2018). "A final limitation is that we have investigated the prevalence of HNF1A-MODY only, as the most common form of monogenic diabetes, so the prevalence of other MODY subtypes, such as GCK-, HNF4A- or HNF1B-MODY in Croatia remains unknown." (PMID 29666556, 2018). "Sequencing of HNF1A gene identified 9 rare non-synonymous HNF1A allelic variants, including 3 protein truncating (PTV) and six missense variants, in 9 probands and 5 relatives (1 without diabetes)." (PMID 29666556, 2018). "Similarly, we observed enrichment of genes associated with the molecular genetics of type 2 diabetes (T2D) and Maturity Onset Diabetes of the Young (MODY; e.g. Hnf1a, Hnf4a, Slc2a2, Gck) in βTC6." (PMID 28931935, 2017). "As absolute insulin deficiency is not typical for HNF1A-MODY persons, the development of diabetic ketoacidosis (DKA) in a person with HNF1A-MODY is rare and just two previous cases are described, it is estimated that approximately 80% of MODY are misdiagnosed as type 1 or type 2 diabetes mellitus." (PMID 28105082, 2017). "The optimum treatment for HNF1A/HNF4A maturity‐onset diabetes of the young and ATP‐sensitive potassium (KATP) channel neonatal diabetes, outside pregnancy, is sulfonylureas, but there is little evidence regarding the most appropriate treatment during pregnancy." (PMID 28556992, 2017). "We did not detect a significant association between missense mutations in genes such as HNF1A and HNF4A, which are frequently mutated in early onset diabetes, likely due to the fact that not all missense mutations in these genes are pathogenic." (PMID 29207974, 2017). "In addition, studies on MODY in pregnant women with diabetes were largely limited to the screening of GCK, HNF1A and HNF4A genes." (PMID 28095440, 2017). "Furthermore, T2D genetic risk plays a small role in LADA, with a degree of evidence for the HNF1A locus, highlighting the potential for GRS to contribute towards defining diabetes subtypes." (PMID 28438156, 2017). "Another important reason is the lack of large pedigrees with an autosomal dominant pattern of inheritance of diabetes which would allow classical linkage analysis to be performed and which was used to discover the most common forms of MODY such as GCK, HNF1A and HNF4A7–10." (PMID 29026101, 2017). "The baseline differences between T2DM and HNF1A-MODY group could be prone to and mask some differences in the microbiome profile between diabetes groups." (PMID 27807544, 2016). "In our family, HNF1A-MODY presents clinically as diabetes without dyslipidemia, as reflected by the index patient." (PMID 27142837, 2016).